LDHA (lactate dehydrogenase A)
Diseases named in the same sentence as LDHA in open-access papers (continued):
Sharing a sentence is not in itself a finding about the gene and the disease.
tumor (continued). "Similar expression of PKM2 and LDHA was observed in the UCLH cohort and TMA samples, with a staining score of > 3 in 64% and 73% of tumours, respectively, for PKM2, and in 76% of tumours for LDHA in both cohorts." (PMID 26989901, 2016). "Other target genes, like lactate dehydrogenase A (LDHA) and monocarboxylate transporter 4 (MCT4), can facilitate both the conversion of pyruvate to lactate and the removal of lactate from tumor cells." (PMID 26934324, 2016). "Patients with tumours scoring > 3 for PKM2 or LDHA expression had significantly worse survival compared with those that weakly expressed PKM2 and/or LDHA." (PMID 26989901, 2016). "The activated networks (HIF1A, ESRRA, ESRRG) had many proteins that were increased in tumor tissues that overlapped between the three targets, such as ENO1/ENO2, ALDOA, and LDHA." (PMID 27128972, 2016). "Consistent with the documented role of lactate dehydrogenase-A (LDHA) for CSCs survival and proliferation as well as tumor progression, we observed that knockdown of LDHA decreased the stemness characteristics of the CD133 (+) cells." (PMID 26506419, 2015). "Various other studies had previously demonstrated increased levels of LDHA and PKM2 in tumour tissues and their important role in proliferation and survival of malignant cells." (PMID 25880801, 2015). "Mechanistically, we showed that SUN2 exerts its tumor suppressor functions by decreasing the expression of GLUT1 and LDHA to inhibit the Warburg effect." (PMID 26658802, 2015). "Knockdown of LDHA in HCT116 and HCT15 cells led to a significant reduction in tumor size and tumor weight." (PMID 26062441, 2015). "In summary, the collaborations among LDHA, MYC and SIRT1 can indeed widen the window of miR-34-induced tumor suppression." (PMID 24884974, 2014). "Using quantitative proteomic analysis, we have recently identified a number of proteins, including LDHA, that are deregulated in metastatic compared to primary RCC, and showed that they are involved in pathways related to tumor progression and metastasis." (PMID 24885701, 2014). "To elucidate the role played by ERRα in the glycolytic adaptation of tumor cells, we focused on the regulation of lactate dehydrogenases A and B (LDHA, LDHB) and the LDHA/LDHB ratio." (PMID 23516535, 2013). "Differential expression of proteins was observed between stromal and tumor cells for ENO3, GLUT1, HK2, IDH3A, LDHA and PKM2." (PMID 22412968, 2012). "In the current study, we investigated the expression of GLUT1, LDHA, MCT1 and MCT4 in tumor cells and reactive bystander cells in different HL subtypes and in respect to treatment outcome in a large number of patients." (PMID 23228169, 2012). "Additional experiments on LDH enzyme activity or measurement of tumor lactate levels in fresh tumor tissue from SDHB- and VHL-PHEOs/PGLs will be of great interest for judging the functional impact of elevated LDHA levels in SDHB-PHEOs/PGLs." (PMID 22859959, 2012). "Furthermore, immunohistochemical (IHC) assays were conducted on xenografted tumor sections to assess Ki67, LC3B, p62, cleaved caspase-3, p-LDHA, and LDHA expression." (PMID 41531896, 2026). "Additionally, tumor tissues in the CMSP treatment group exhibited elevated expression levels of LC3B, p62, and cleaved caspase-3, alongside a reduction in p-LDHA expression, when compared to the control group." (PMID 41531896, 2026). "Consistent with the in vitro observations, the reduced tumor development in LDHA‐depleted cells was rescued only by overexpression of LDHA‐WT, whereas LDHA‐2KR failed to restore tumor growth." (PMID 41190808, 2026). "Elevated LDHA activity supports rapid ATP production under hypoxic conditions, maintains NAD+ regeneration, and promotes lactate accumulation, creating an acidic tumor microenvironment (TME) that favors invasion and immune evasion." (PMID 41977425, 2026).
tumor (continued). "In this review, we summarize how key glycolytic regulators, including GLUT1, HK2, PFKFB3, PDK1, and LDHA, are controlled by oncogenic, microenvironmental, and non-coding RNA-mediated pathways to reshape tumor metabolism." (PMID 42317327, 2026). "Tumor endothelial cells (ECs), under hypoxic conditions, exhibit enhanced glycolytic flux, evidenced by the upregulation of glycolytic enzymes such as hexokinase 2 (HK2), PKM2, and LDHA." (PMID 41281744, 2025). "Consequently, tumor cells with hyperlactylated MRE11/NBS1 display marked chemoresistance, and pharmacologic blockade of lactate production (via LDHA inhibition) restores therapeutic sensitivity." (PMID 41583433, 2025). "Furthermore, subsequent research demonstrated that miR-218 suppresses tumor growth and angiogenesis through the downregulation of HK2 and LDHA expression in vivo." (PMID 40661148, 2025). "In terms of therapy, these insights suggest that targeting metabolic pathways, such as inhibiting LDHA or PFKP to disrupt glycolysis, or using MTORC1 inhibitors like rapamycin, may alleviate tumor growth and invasion." (PMID 40464853, 2025). "For example, inhibiting LDHA or lactate transporters in combination with anti-CTLA-4 therapy leads to increased infiltration of cytotoxic T cells and reduced regulatory T cells, thereby improving anti-tumor immune responses." (PMID 40535811, 2025). "This study reveals that lactylation links tumour cell metabolism and DNA damage repair, serving as a key regulatory factor in HRR where chemotherapy combined with CBP or LDHA inhibitors could enhance sensitivity and provide a more efficient treatment." (PMID 40984037, 2025). "The results showed that LDHA was highly expressed in tumor tissues in both nonmatched and matched BCa patient tissue samples." (PMID 41199784, 2025). "Mechanistically, GPR37 promotes LDHA expression and glycolysis by activating the Hippo pathway, which increases H3K18la levels, upregulates chemokine CXC motif ligand 1 (CXCL1) and CXCL5, and enhances tumor cell migration." (PMID 40584966, 2025). "Additionally, we analyzed the expression of CSC genes in these tumours and found that the expression levels of CD133, CD44 and ALDHA1 were consistent with the effects of FOXO3a/miR4259 signaling on LDHA expression." (PMID 39930542, 2025). "PSTMB can inhibit LDHA activity and reduce lactate formation without affecting LDHA expression, providing a new option for the development of novel drugs targeting tumor metabolism." (PMID 41041328, 2025). "Furthermore, 5'tRF-GlyGCC/LDHA axis induces macrophage infiltration and polarization toward an M2 phenotype, mediated by the chemokine CCL7, thereby reshaping the tumor microenvironment." (PMID 41309487, 2025). "Based on this, we speculate that NQO1 may interact with multiple key glycolytic enzymes, such as lactate dehydrogenase A (LDHA), in CRC, potentially regulating lactate production and tumor metabolism." (PMID 39939940, 2025). "NADH‐competitive LDHA inhibitors, including Gossypol (also known as AT‐101), FX11 (3,3'‐dihydroxy‐6‐methyl‐7‐(phenylmethyl)‐4‐propyl‐naphthalene‐1‐carboxylic acid), and Quinolinesulfonamide, have also been demonstrated to inhibit tumor cell proliferation." (PMID 40443721, 2025). "Given the central role of metabolic pathways in GBM progression, targeting alternative Warburg effect regulators like HK2, LDHA, or MCT1, which are more tumor-specific, may offer greater therapeutic benefits." (PMID 40563757, 2025). "Soman effectively inhibited STAT phosphorylation in an ROS-independent manner, resulting in the decreased expression of glycolytic enzymes (HK2, PKM2, and LDHA) and activities of PK and LDH, leading to the suppression of aerobic glycolysis, cancer cell proliferation, and tumor growth." (PMID 40002413, 2025).
tumor (continued). "Furthermore, CD63 exhibited significantly higher expression levels in the malignant cell clusters of immune cells and demonstrated a strong correlation with glycolytic genes, such as LDHA and LDHB, in tumor cells." (PMID 41573746, 2025). "Forced expression of SMC4 significantly upregulated LDHA protein levels, whereas SMC4 knockdown resulted in marked LDHA downregulation, suggesting SMC4 may regulate tumor energy metabolism." (PMID 40933894, 2025). "LDH has two main isozymes, LDHA and LDHB, which are overexpressed in tumor cells." (PMID 40612109, 2025). "In hypoxic tumor cores, activating HIF-1 prompts nuclear translocation and transcriptional upregulation of glycolytic machinery: glucose transporters (glucose transporter 1 (GLUT1)/GLUT3), HK2, PFK, and LDHA—collectively amplifying glycolytic flux." (PMID 41181157, 2025). "On the other hand, enforced expression of FOXO3a in PANC-1/GEM cells decreased the LDHA expression, CSC phenotypes, tumour initiating capacity and suppressed gemcitabine resistance; further abolishment of miR-4259 by anti-miR-4259 significantly restored the effects of FOXO3a in PANC-1/GEM cells." (PMID 39930542, 2025). "In the tumor microenvironment, where serine availability is limited, PKM2 coordinates with the c-Myc-responsive long non-coding RNA gLINC to assemble a metabolic enzyme complex comprising PGK1, PGAM1, ENO1, and LDHA." (PMID 40842995, 2025). "Lactate from LDHA-overexpressing tumors may suppress CXCL13-mediated immune cell recruitment, creating a “cold” tumor microenvironment." (PMID 40260244, 2025). "NADH-competitive inhibitors of LDHA, such as Gossypol (also known as AT-101), FX11 (3-dihydroxy-6-methyl-7-(phenylmethyl)-4-propylnaphthalene-1-carboxylic acid), and quinoline-3-sulfonamide, have also been proven to inhibit tumor cell proliferation." (PMID 40034817, 2025). "Furthermore, protein expression levels in the tumor tissue revealed that miR-6126 inhibits the expression of Warburg effect-related signaling proteins such as GRP78, HIF1α, GLUT1, and LDHA but induces PTEN expression." (PMID 40959569, 2025). "To investigate the effect of exosomal LDHA activity on tumor progression, we intravenously administered Ctrl-EVs, LDHA-EVs, and GNE140-treated EVs to U87-MG tumor-bearing mice and assessed EV distribution, tumor progression, and intracranial ATP, lactate, and LDHA levels." (PMID 40093910, 2025). "Furthermore, we detected significantly reduced levels of glycolytic enzymes (HK2 and LDHA) and markedly attenuated phosphorylation of PI3K and AKT in tumor samples with P3H4 silencing." (PMID 41220593, 2025). "FX11 suppresses both LDHA and LDHB, in contrast to GNE-140, which may have a wider effect on several tumor cell types." (PMID 40917751, 2025). "Curcumin exerts broad-spectrum antitumor effects by precisely intervening in the glucose metabolism of tumor cells, notably by suppressing key glycolytic enzymes such as HK2, PKM2, and LDHA, as well as GLUT1 and MCTs, thereby effectively reversing the Warburg effect." (PMID 41515171, 2025). "In addition, the expression levels of HK2, LDHA, Glut1, and PDK1 were significantly decreased in the tumor tissues of MKN45R and HGC27R cells in the sh-SLC7A5 group." (PMID 40133832, 2025). "Research has demonstrated that activation of the mTOR pathway increases the expression of HIF-1α and c-Myc, further upregulating glucose transporter 1 (GLUT1), glycolysis-related enzymes, LDHA, MCT1, and MCT4, thereby promoting lactate production in tumor cells." (PMID 40034817, 2025). "3.Therapeutic Implications: This study showed that one of the discovered LMRGs, lactate dehydrogenase A (LDHA), may be knocked down to suppress tumor development in vivo in mouse models, as well as tumor proliferation and migration in vitro." (PMID 39968078, 2025).
tumor (continued). "LDHA is induced by hypoxia or MYC activation, enabling glycolysis to become the primary source of ATP production in response to oxygen deprivation and the tumor’s ability to recruit new blood vessels." (PMID 40941984, 2025). "P3H4 silencing suppresses tumor growth both in vitro and in vivo while simultaneously downregulating key glycolytic enzymes HK2 and LDHA, suggesting a potential metabolic vulnerability that could be therapeutically exploited." (PMID 41220593, 2025). "After R-mPDV/PDV/siL treatment, LDHA mRNA downregulation by more than 80% and lactate accumulation were significantly reduced in 4T1 tumors, along with activation of AMPK-ULK1 pathway and autophagy in tumor cells, and reduction of G-CSF and GM-CSF production." (PMID 39990210, 2025). "Interestingly, lactate dehydrogenase A (LDHA) enhances ferroptosis in CRC cells and strengthens CD8+ T cell anti‐tumour activity." (PMID 41399129, 2025). "Not surprisingly, the lactate production in the tumor was decreased after Oxamate treatment or LDHA knockdown." (PMID 38711083, 2024). "Moreover, pathway analysis revealed that SPP1+APOE+ TAM were regulated by the HIF-1 signaling pathway, inducing expression of VEGFA, LDHA, and ALDOA46,47, which not only promotes hypoxia but is another approach to induce EMT in tumor cells." (PMID 39075108, 2024). "We observed that cancer cells overexpress LDHA compared with nonmalignant cells within the tumor, indicating its preferential utilization by tumor cells for glycolysis." (PMID 39225102, 2024). "To further delineate the crucial target gene, we initially conducted a comparative analysis of SPP1, NDRG1, SFN and LDHA mRNA expression levels in clinical samples of HCC and adjacent non-tumor tissues, as well as various HCC cell lines and normal liver cell lines." (PMID 39066845, 2024). "The administration of the LDHA inhibitor FX-11 leads to a notable augmentation of tumour-infiltrating CD8 + T and NK cells in the mice model, thereby potentially enhancing the responsiveness of tumours to anti-PD-1 immunotherapy in the MPS2 subtype." (PMID 38555429, 2024). "Under hypoxia, tumor cells do not use pyruvate in the mitochondria but convert it to lactate by lactate dehydrogenase (LDHA)." (PMID 39475618, 2024). "Lactate dehydrogenase A (LDHA) and LDHB are essential metabolic products that promote tumor growth." (PMID 38764020, 2024). "Additionally, knockdown of Serinc2 inhibited tumor growth and reduced the protein expression of c‐Myc, PFKP, LDHA, and PDK1 in vivo." (PMID 39417376, 2024). "In hypoxic tumor microenvironments, HIF-1α can induce the activation of LDHA." (PMID 38841361, 2024). "Based on the Spearman correlation analysis in GEPIA, we identified a significant correlation between STAT1 and LDHA/LDHB/FGF1/FGF2 in tumor tissues but not in normal tissues." (PMID 38764020, 2024). "We found several molecules that are significant in tumor initiation and treatment by immune checkpoint analysis, such as lymphocyte-activation gene 3 (LAG3), PTPRC, HAVCR2, B2M, LDHA, and LDHB, which may be used as a reference for tumor immunotherapy." (PMID 39014082, 2024). "Genes involved in glycolysis (ALDOA, LDHA, PGK1, PFKL, PGM1) and other metabolic processes (GPX4, PRDX4, ACO2, ASPH, IDH2, SQLE, NPC2, SPTSSA) were upregulated in primary tumor cells, suggesting that the metabolism in primary tumors was distinct from that in their matched metastasis." (PMID 39225101, 2024). "Downregulating the expression of LDHA, LDHB, and MCT inhibits the production and influx/efflux of lactate in cancer cells, promoting the repolarization of macrophages from the tumor‐supportive M2 phenotype to the tumor‐suppressive M1 phenotype." (PMID 39415848, 2024). "As expected, stiripentol treatment did not exhibit additional anti-tumor effects in LDHA-depleted tumors, supporting our above in vivo findings that LDHA is the key target of stiripentol." (PMID 38443336, 2024).
tumor (continued). "In addition, studies on individuals with hereditary LDHA deficiency revealed that the lack of this enzyme did not cause symptoms under normal circumstances, hence supporting the notion that hLDH5 could be a safe target for anti-tumor agents." (PMID 38731601, 2024). "Studies have shown that the regulation of glycolysis involves glucose transporter type 1 (GLUT1), hexokinase 2 (HK2), the mitochondrial translocator protein (TSPO), lactate dehydrogenase A (LDHA), hypoxia‐inducible factor 1‐alpha (HIF‐1⍺), the tumor microenvironment, and mitochondrial genes." (PMID 39639571, 2024). "Consistently, 13 increased the NADH content, decreased the lactate levels in tumor cells, and failed to inhibit the cell growth of HCT116 cells with LDHA deficiency." (PMID 38731601, 2024). "Lactate dehydrogenase A (LDHA) serves as a pivotal enzyme catalyzing the terminal step of the Warburg effect, converting pyruvate and NADH to lactate, thus playing a crucial role in tumor metabolism and growth." (PMID 39393052, 2024). "CM from LDHA-inhibited (genetically and pharmacologically) CT2A and GL261 cells impaired the expression of a pro-tumor macrophage marker arginase 1 (Arg1) and the percentage of pro-tumor CD68+CD206+ cells in Raw264.7 macrophages." (PMID 38443336, 2024). "Glabridin induces tumor cell apoptosis by upregulating the pro-apoptotic gene Bax and downregulating the anti-apoptotic gene Bcl-2 while inhibiting glycolysis by reducing HK2 and LDHA expression." (PMID 39723390, 2024). "Vitamin C‐dependent inhibition of LDHA in PDAC might also decrease TME lactate concentration, thus lowering the acidic PDAC tumor microenvironment, favoring the action of T‐lymphocytes and opening the door to the use of novel biological immunotherapies." (PMID 38425123, 2024). "Notably, glycolysis enzymes (GPI, LDHA, LDHB, TPI1, and ALDOA) showed specific enrichment in exosomes from the primary tumor." (PMID 38419074, 2024). "The results showed that P300, LDHA and LDHB were all overexpressed in tumor samples." (PMID 37950222, 2023). "This suggests that overexpression of LDHA and PFKP could be an important factor not only for tumor progression but also for the development of metastases." (PMID 37326348, 2023). "In addition, some SNO proteins can participate in the proliferation, metastasis, and apoptosis of CRC by regulating the tumor endocrine and metabolic pathways, such as PKM, GAPDH, LDHA, GLUD1, and PTGES3." (PMID 37124724, 2023). "The results showed that compared to the sh-NC group, the lactate and ATP contents in tumor tissues were significantly reduced in the sh-LHX9 group, and the mRNA and protein expression of glycolysis-related genes (GLUT1, HK2, LDHA, and PDK1) were also significantly reduced." (PMID 37980488, 2023). "Consistent with above findings, tumor volume analysis indicated that APOL3-OE of CT26 with treatment of RSL3 significantly increased the antitumor ability of PD-1 inhibitor in vivo and this effect can be diminished by co-overexpression of LDHA." (PMID 36923931, 2023). "Real-time qPCR analysis of glucose transporter and glycolytic genes in the xenograft tumor tissues showed that ACE2 overexpression suppressed the mRNA levels of SLC2A1, HK2, ENO1, PFKL, LDHA, and PDK1, while inhibition of Mas receptor with A779 restored the expression of glycolytic components." (PMID 37215979, 2023). "LDHA and PFKP expression levels were significantly higher in tumor tissues than in HCTs (FC = 4.3 for LDHA and FC = 27.2 for PFKP); interestingly, the expression levels of both proteins were even higher in CC metastases than in HCTs (FC = 10.4 and 42.7, respectively)." (PMID 37326348, 2023).